HDAC2 (histone deacetylase 2)
Diseases named in the same sentence as HDAC2 in open-access papers (continued):
Sharing a sentence is not in itself a finding about the gene and the disease.
Autoimmunity (4 papers, 2017 to 2021). The occurrence of an immune reaction against the organism's own cells or tissues. "In contrast, HDAC2 inhibition moderately suppressed the inflammatory pathways and scored lesser in inducing the pathways associated with autoimmunity." (PMID 35222229, 2021). "Calcitriol was shown to ameliorate autoimmunity and exhibit transcriptional repression of the parathyroid hormone through recruitment of HDAC2." (PMID 29776409, 2018). "The thylcytosine dioxygenase TET2 could promote DNA demethylation to control the production of IFN-γ and IL-17 in autoimmunity, and was required to resolve inflammation by recruiting HDAC2 and repressing transcription of IL-6 through histone deacetylation." (PMID 28915632, 2017).
colorectal adenocarcinoma (4 papers, 2016 to 2025). The most common type of colorectal carcinoma. "Selective knockdown of HDAC1, HDAC2, and a combination of both HDAC1 plus HDAC2 has been reported to increase the expressions of P-gp, MRP-1, and MRP2 in cell lines derived from human colorectal adenocarcinomas (HCT-8 and HCT-116)." (PMID 31191307, 2019).
cutaneous T cell lymphoma (4 papers, 2008 to 2022). "A previous study showed that histone deacetylase (HDAC) inhibitors attenuate ALI in mice, and HDAC2/6 has been implicated in the therapeutic effects of vorinostat for the treatment of cutaneous T cell lymphoma (CTCL)." (PMID 32176725, 2020). "Expression of HDAC1, HDAC2, HDAC6, and acetylated H4 (H4ace) in different subtypes of cutaneous T-cell lymphoma (CTCL) (n = 73)." (PMID 18671804, 2008).
Hypertension (4 papers, 2019 to 2025). The presence of chronic increased pressure in the systemic arterial system. "In our current study, we found that MS-275, a class I HDAC-selective inhibitor (HDAC1, HDAC2, and HDAC3), lowered blood pressure, reduced blood vessel thickness, and inhibited inflammation in an Ang II-induced hypertensive animal model." (PMID 30830950, 2019). "In summary, HDAC5 plays an important role in the early pathogenesis and vascular remodelling of ANG II‐induced hypertension, HDAC6 affects vascular relaxation function, while HDAC1 and HDAC2 regulate the transcription of genes related to blood pressure regulators." (PMID 40497340, 2025). "However, when the heart is subjected to stress such as hypertension or phenylephrine, the interaction between PP2A and HDAC2 is disrupted." (PMID 40497340, 2025). "In hypertension induced by an HFD, HDAC1 and HDAC2 are activated, leading to nuclear accumulation." (PMID 40497340, 2025).
multiple myeloma (4 papers, 2008 to 2023). "Most of the HDAC inhibitors that are currently under investigation in clinical trials or have not been approved yet, such as panobinostat (approved for the therapy of multiple myeloma in 2015 by the EMA), inhibit a broad variety of HDACs including HDAC2." (PMID 35055045, 2022). "Interestingly, we found that alteration of HDAC expression in bortezomib-resistant myeloma cells is heterogeneous, such that HDAC3, 4, 5, 7, 9, 10, and 11 are downregulated while HDAC2 and 6 are upregulated." (PMID 34888496, 2021).
ovarian tumors (4 papers, 2014 to 2024). "Co-immunoprecipitation (coIP) analysis demonstrated an interaction between EZH2 and HDAC2 in ARID1A-mutated Ovarian Tumor-derived Cell Line 21G (TOV21G), and the restoration of wild-type ARID1A disrupted this interaction, suggesting that EZH2 did not interact with HDAC2 in ARID1A wild-type cells." (PMID 38794190, 2024). "Higher-grade ovarian tumors are characterized by upregulation of HDAC2." (PMID 39063083, 2024).
pancreatic ductal adenocarcinoma (4 papers, 2015 to 2023). An infiltrating adenocarcinoma that arises from the epithelial cells of the pancreas. "In pancreatic ductal adenocarcinoma, HDAC2 enhances the disassembly of primary cilia, likely by promoting Aurora-A expression." (PMID 37878054, 2023). "Previous research proved that high HDAC2 expression confers drug resistance toward the topoisomerase II inhibitor etoposide in pancreatic ductal adenocarcinoma cells." (PMID 37248230, 2023).
Parkinson disease (4 papers, 2012 to 2024). A progressive degenerative disorder of the central nervous system characterized by loss of dopamine producing neurons in the substantia nigra and the presence of Lewy bodies in the substantia nigra and locus coeruleus. "A previous study reported a significant upregulation of HDAC2 expression in laser-captured nigral microglia in Parkinson’s disease." (PMID 31796106, 2019).
skin cancer (4 papers, 2013 to 2023). "Given a potential tumour maintaining role of HDAC1/2 through association with p63 in squamous cell carcinoma, HDAC1 and HDAC2 might also be promising targets in skin cancer treatment." (PMID 24240174, 2013). "By ablating different combinations of Hdac1 and Hdac2 alleles in the epidermis using K5-Cre, we revealed a specific role of HDAC1 in epidermal development and skin cancer." (PMID 24240174, 2013). "We therefore examined the effect of ablation of HDAC1 and HDAC2 in the genetic K5-SOS skin tumour model." (PMID 24240174, 2013). "The study further suggested that SFN and iberin reduced the viability of skin cancer cells (A375, Hs294T, and B16F10) and decreased the expression of HDACs (HDAC1, HDAC2, HDAC4, and HDAC6)." (PMID 36765652, 2023). "The mechanistic insights revealed a decreased methylation ratio of CpG dinucleotides in the promoter region of Nrf2 in SFN-treated skin cancer cells, and SFN also attenuated the expression of HDACs (HDAC1, HDAC2, HDAC3, and HDAC4) and DNMTs (DNMT1, DNMT3a, and DNMT3b)." (PMID 36765652, 2023). "Surprisingly, ablation of HDAC1 but not HDAC2 in a skin tumour model leads to accelerated tumour development." (PMID 24240174, 2013).
urothelial carcinoma (4 papers, 2014 to 2021). A malignant neoplasm derived from the transitional epithelium of the urinary tract (urinary bladder, ureter, urethra, or renal pelvis). "In urothelial carcinoma, in particular, the importance of class I HDACs, especially of HDAC1 and HDAC2, has been underlined by recent dedicated studies, in keeping with general thought." (PMID 31052182, 2019). "Additionally, a 2016 study showed that the inhibition of HDAC2 successfully inhibited cell proliferation and suggested that the inhibition of HDAC2 may be a promising therapy for urothelial carcinoma." (PMID 33778495, 2021). "High HDAC expression levels were found in 40 to 60% of all investigated urothelial carcinomas (HDAC-1: 40%, HDAC-2: 42%, HDAC-3: 59%)." (PMID 24624923, 2014).
acute liver failure (3 papers, 2018 to 2021). Rapid deterioration of liver function causing encephalopathy and coagulopathy. "The HDAC2 inhibitor CAY10683 achieves the goal of treating acute liver failure by protecting the damaged intestinal mucosa and reducing intestinal endotoxemia." (PMID 31183000, 2019). "In conclusion, modulations of histone deacetylase 2 via the mitochondrial apoptosis pathway offer a protective effect in acute liver failure." (PMID 31183000, 2019). "The purpose of this study was to investigate the modulation of histone deacetylase 2 (HDAC2) on mitochondrial apoptosis in acute liver failure (ALF)." (PMID 31183000, 2019). "The purpose of this study was to investigate the protective mechanism of HDAC2 inhibitor CAY10683 on intestinal mucosal barrier in acute liver failure (ALF)." (PMID 29725271, 2018). "In fact, this preliminary study only demonstrated that inhibition of HDAC2 expression could alleviate apoptosis in acute liver failure." (PMID 31183000, 2019). "In this study, we aimed to investigate the effect of HDAC2 on TNF-α/D-gal-induced injury in the LO2 cell line and in the LPS/D-gal-induced ALF rat model and to further explore the HDAC2 epigenetic regulation on the mitochondrial apoptosis pathway in acute liver failure." (PMID 31183000, 2019).
anemia (3 papers, 2018 to 2024). A reduction in the number of red blood cells, the amount of hemoglobin, and/or the volume of packed red blood cells. "Knockout of histone deacetylases HDAC1 or HDAC2 affects hematopoiesis, while simultaneous knockout of HDAC1 and HDAC2 results in severe HSC defects, leading to anemia and reduced blood cell counts, indicating functional redundancy between HDAC1 and HDAC2 in hematopoiesis." (PMID 39445003, 2024).
autism spectrum disorder (3 papers, 2022 to 2026). A spectrum of developmental disorders that includes autism, and Asperger syndrome. "For instance, Tbr1, Chd7, and Hdac2 are autism spectrum disorder risk genes." (PMID 36791184, 2023). "HDAC2’s differential expression in the central nervous system makes it an appealing therapeutic target for chronic neurological diseases like autism spectrum disorder." (PMID 35877665, 2022). "The differential expression of HDAC2 in CNS makes it an alluring therapeutic target for chronic neurological disorders like ones in autism spectrum disorder." (PMID 35877665, 2022).
B cell lymphomas (3 papers, 2014 to 2023). "Our study raises the prospect of using selective HDAC1 and HDAC2 inhibitors for the treatment of BL and other B cell lymphomas with Myc deregulation, with possibly less side effects than pan-HDACis currently used." (PMID 27886239, 2016). "In this study, we used targeted conditional deletion of Hdac1 and Hdac2, to investigate the functional role of these enzymes in the Eμ-myc murine B cell lymphoma model." (PMID 27886239, 2016). "Here, we investigated the functional role of Hdac1 and Hdac2 using the Eμ-myc mouse model of B cell lymphoma." (PMID 27886239, 2016). "In view of these observations, we assessed the functional role of Hdac1 and Hdac2 in the development and progression of Eμ-myc driven B cell lymphomas." (PMID 27886239, 2016). "We further investigated the function of Hdac1 and Hdac2 in the Eμ-myc murine B cell lymphoma model." (PMID 27886239, 2016).
bronchopulmonary dysplasia (3 papers, 2014 to 2023). Bronchopulmonary dysplasia is a chronic respiratory disease that results from complications related to lung injury during the treatment of infant acute respiratory distress syndrome in low-birth-weight premature infants or from abnormal lung development in older infants. "Consistent with our results, reduced HDAC2 activity and levels were observed in the lungs of rats in a bronchopulmonary dysplasia animal model by injecting LPS into the amniotic cavity." (PMID 28578424, 2017).
cardiac arrhythmia (3 papers, 2013 to 2025). Any disturbances of the normal rhythmic beating of the heart or MYOCARDIAL CONTRACTION. "The knockout of both HDAC1 and HDAC2 in the heart can lead to severe arrhythmia and dilated cardiomyopathy, whereas the deletion of one gene does not affect heart development, indicating functional redundancy between HDAC1 and HDAC2." (PMID 40102393, 2025).
Cirrhosis (3 papers, 2021 to 2024). A chronic disorder of the liver in which liver tissue becomes scarred and is partially replaced by regenerative nodules and fibrotic tissue resulting in loss of liver function. "Furthermore, we conducted an analysis of clinical follow-up records from 105 HCC patients to explore the correlation between HDAC2 expression and clinicopathological features, including tumor sizes, cirrhosis, HBV infection, and microvascular invasion." (PMID 39147759, 2024).
diabetic kidney disease (3 papers, 2014 to 2024). Progressive kidney disorder caused by vascular damage to the glomerular capillaries, in patients with diabetes mellitus. "HDAC2 is highly expressed in diabetic kidney disease (DKD) and mediates the development of renal fibrosis through a variety of mechanisms." (PMID 38929505, 2024).
dilated cardiomyopathy (3 papers, 2017 to 2025). Cardiomyopathy which is characterized by dilation and contractile dysfunction of the left and right ventricles. "Notably, cardiac-restricted deletion of both HDAC1 and HDAC2 caused dilated cardiomyopathy accompanied by upregulation of genes encoding skeletal muscle-specific contractile proteins." (PMID 28394251, 2017).
Ewing sarcoma (3 papers, 2018 to 2025). A small round cell tumor that lacks morphologic, immunohistochemical, and electron microscopic evidence of neuroectodermal differentiation. "We show that HDAC2 is overexpressed in Ewing sarcoma cells and that an HDAC inhibitor, Panobinostat, is cytotoxic to Ewing sarcoma cells both alone and when combined with standard of care." (PMID 39518006, 2024). "We previously demonstrated that histone deacetylases HDAC2/3 are directly recruited by EWS/FLI to mediate transcriptional repression, with vorinostat treatment of Ewing sarcoma cell lines blocking EWS/FLI–mediated transcriptional repression but not activation." (PMID 30559927, 2018).
gastric tumors (3 papers, 2019 to 2025). "We report the following new findings with this case: (i) gastric tumors mimic the gastrointestinal mesenchyme in the embryonic period; (ii) nuclear expression of PD-L1 and HDAC2 were observed in the spindle cell component of a gastroblastoma." (PMID 36803776, 2023).
Huntington disease (3 papers, 2018 to 2021). Huntington disease (HD) is a rare neurodegenerative disorder of the central nervous system characterized by unwanted choreatic movements, behavioral and psychiatric disturbances and dementia. "Hdac2 belongs to Huntington's disease pathway, which was significantly altered at 24 hpi." (PMID 34277631, 2021). "Finally, Bax, Hdac2 and Sp1, involved in apoptosis and transcription, are found among the Huntington’s disease-specific genes affected by LPS and LPS + IFNγ." (PMID 30382133, 2018). "We show that like AD, disruption of Tip60 HAT/HDAC2 balance with concomitant epigenetic repression of common Tip60 target neuroplasticity genes occurs early in multiple types of Drosophila ND models such as Parkinson’s Disease (PD), Huntington’s Disease (HD) and Amyotrophic Lateral Sclerosis (ALS)." (PMID 33106538, 2020). "We show that disruption of Tip60 HAT/HDAC2 balance with concomitant epigenetic repression of common neuroplasticity Tip60 target genes is an early event in multiple types of Drosophila ND models that include Parkinson’s Disease (PD), Huntington’s Disease (HD) and Amyotrophic Lateral Sclerosis (ALS)." (PMID 33106538, 2020). "Similarly, decreased expression of the Huntington’s disease-related genes Sp1, Hdac2 and Bax, as a result of both treatments could provide some clues about the underlying disease mechanisms." (PMID 30382133, 2018).
idiopathic pulmonary fibrosis (3 papers, 2020 to 2024). Idiopathic pulmonary fibrosis (IPF) is a nonneoplastic pulmonary disease that is characterized by the formation of scar tissue within the lungs in the absence of any known cause. "Furthermore, the expression levels of HDAC1 and HDAC2 are significantly elevated in fibrotic lesions of idiopathic pulmonary fibrosis (IPF) lung tissues and primary IPF fibroblasts." (PMID 39193364, 2024).
inflammatory bowel disease (3 papers, 2018 to 2025). A spectrum of small and large bowel inflammatory diseases of unknown etiology. "Silencing of HDAC2 in Caco-2 cells additionally decreases expression of the transporter of serotonin, whose expression is commonly dysregulated in inflammatory bowel disease." (PMID 33842512, 2021). "Future research could further explore the application of HDAC2 inhibitors in other chronic inflammatory diseases (such as inflammatory bowel disease) and develop specific therapeutic strategies targeting HDAC2 to improve patients' pain and quality of life." (PMID 40337468, 2025).
Insulin resistance (3 papers, 2004 to 2024). Increased resistance towards insulin, that is, diminished effectiveness of insulin in reducing blood glucose levels. "For instance, the binding between HDAC2 and insulin receptor substrate-1 (IRS-1) can impair insulin receptor-mediated tyrosine phosphorylation, leading to insulin resistance." (PMID 39596347, 2024).
ischemia (3 papers, 2019 to 2025). A hypoperfusion of the BLOOD through an organ or tissue caused by a PATHOLOGIC CONSTRICTION or obstruction of its BLOOD VESSELS, or an absence of BLOOD CIRCULATION. "In ischemia, specific HDAC isoforms (e.g., HDAC1, HDAC2, HDAC3, and HDAC6) have been implicated in microglial activation, glial reactivity, and disruption of immune balance." (PMID 40867911, 2025). "Compared to baseline, levels of Edn1 mRNA in WT and HDAC 2-/- kidneys were elevated several-fold at 24 h post-ischemia, though levels in WT mice were significantly higher than in HDAC2-/- mice (p = 0.046)." (PMID 33907245, 2021). "HDAC1 and HDAC2 are localized mainly in the nuclei of neurons, astrocytes and oligodendrocytes, but their expression may change after ischemia." (PMID 31200484, 2019). "Administration of corin or vehicle (DMSO), at 10 mg/kg/day at 16- and 1-h pre-ischemia, did not result in biochemical renal injury in either HDAC1-/- or HDAC2-/- mice." (PMID 33907245, 2021).
kidney cancer (3 papers, 2021 to 2025). Primary or metastatic malignant neoplasm involving the kidney. "HDAC1 and HDAC2 are necessary for the growth and survival of kidney cancer cells." (PMID 41407823, 2025). "Studies with SAP30 gene have shown its relationship with histone deacetylase process in eukaryotes that induces Sin3, the histone deacetylases HDAC1 and HDAC2, and acting as a transcription factor for NETO2 gene in kidney cancer." (PMID 34646299, 2021).
liposarcoma (3 papers, 2019 to 2021). A usually painless malignant tumor that arises from adipose tissue. "HDAC4 and HDAC9 are upregulated in leiomyosarcoma, and HDAC2 is activated in liposarcomas." (PMID 35008848, 2021).
muscular dystrophy (3 papers, 2019 to 2022). Muscular dystrophy (MD) refers to a group of more than 30 genetic diseases characterized by progressive weakness and degeneration of the skeletal muscles that control movement. "BRMS1 and HDAC2 are part of a histone deacetylase complex (HDAC), and the predicted disruption of this pathway indeed fits with studies that linked muscular dystrophies to deregulated HDAC activity." (PMID 31114913, 2019).
oral cancer (3 papers, 2018 to 2023). "In another study, it was also reported that HDAC2 expression led to invasion/migration of human oral cancer cell lines via HIF-1α stability regulation." (PMID 30135512, 2018).
osteoporosis (3 papers, 2021 to 2023). A condition of reduced bone mass, with decreased cortical thickness and a decrease in the number and size of the trabeculae of cancellous bone (but normal chemical composition), resulting in increased fracture incidence. "This miRNA participates in osteoporosis through one of its targets, histone deacetylases 2 (HDAC2), a pivotal mediator of osteoblastic differentiation that is overexpressed in the presence of low levels of miRNA-455-3p." (PMID 36835184, 2023). "For instance, in the case of osteoporosis, SIRT6-mediated deacetylation and downregulation of HDAC2 were both proved to be helpful to mitigate osteoporosis, while the former led to increased ERα level and the latter led to promoted acetylation of histone H3." (PMID 34326880, 2021). "Other ways like electroacupuncture (EA) was proved to downregulate the expression of HDAC2 and promoted the acetylation of histone H3 as well, which lead to improvement of the bone mineral density and trabecular morphology in ovariectomy-induced osteoporosis." (PMID 34326880, 2021).
peripheral nerve injury (3 papers, 2019 to 2024). Injury to a peripheral nerve. "Reduced HDAC2 occupancy at the Cacna2d1 promoter is involved in peripheral nerve injury-induced transcriptional activation of Cacna2d1 in the DRG." (PMID 39357831, 2024). "Thus, our research confirmed that HDAC2 was involved in mechanical and thermal hyperalgesia induced by peripheral nerve injury." (PMID 31024248, 2019).